BRAF (B-Raf proto-oncogene, serine/threonine kinase)
Diseases named in the same sentence as BRAF in open-access papers (continued):
Sharing a sentence is not in itself a finding about the gene and the disease.
melanoma (continued). "We demonstrate intracranial tumor responses to REGO + BRAF/MEKi in BRAFV600-mutant melanoma patients with active and symptomatic MBM that were pretreated systemically as well as locally in a number of patients." (PMID 39682270, 2024). "Our findings delineate the molecular mechanisms involving polyamine-EIF5A hypusination-mitochondrial respiration pathway conferring BRAF inhibitor resistance in melanoma." (PMID 38965534, 2024). "We and others also noticed recovery of ERK1/2 phosphorylation after the use of a BRAF inhibitor in resistant melanoma cell lines." (PMID 39175042, 2024). "Our study provides evidence supporting the therapeutic potential of the anti-HER2 drug conjugate RC48, either alone or in combination with dabrafenib, for treating HER2-positive and BRAF-mutant melanoma." (PMID 38594618, 2024). "The presence of BRAF V600E alteration is helpful in differentiating low-CSD melanomas from melanomas of the Spitz lineage." (PMID 38247727, 2024). "Comparison of the systemic neoadjuvant treatment approaches in advanced melanoma patients: BRAF/MEK-targeted therapy and immunotherapy." (PMID 38540282, 2024). "MEK inhibitors such as binimetinib, cobimetinib, and trametinib are aimed at melanomas and NSCLC with BRAF mutations." (PMID 39337925, 2024). "CD36 serves as an important target for melanoma as it overexpresses in drug-tolerant cells of BRAF or MEK therapies." (PMID 39062552, 2024). "Multiple therapies have been developed to treat BRAF-mutant melanomas through the characterization and identification of numerous BRAF mutations." (PMID 39336897, 2024). "The COMBI-d (NCT01584648) clinical trial was the first BRAF-mutant melanoma-focused trial to evaluate the efficacy of the combination of dabrafenib plus trametinib against dabrafenib alone." (PMID 38539548, 2024). "IL6 has been identified as a driver of drug resistance, while increased level of CCL2 was detected in resistant melanoma cells after treatment with a BRAF inhibitor." (PMID 39175042, 2024). "These found have led to the development approval of three BRAF inhibitors as well as five combinations of a BRAF inhibitor to manage cancer such as anaplastic thyroid cancer, melanoma, non-small cell lung cancer and colorectal cancer." (PMID 38795180, 2024). "Combining targeted therapy and immunotherapy in patients with BRAF-mutant melanoma has yielded limited effectiveness." (PMID 39336897, 2024). "Ultimately, the upregulation of both p300 and NONO favors the rebound of pERK1/2 and the development of subsequent resistance of melanoma cells to BRAF inhibitors." (PMID 38493226, 2024). "Increasingly, single agent PD1 is being recognised as the de facto standard of care in the adjuvant treatment of melanoma for patients with BRAF wild-type tumours." (PMID 38180677, 2024). "Compared to other observed groups, the strongest immunoreactivity was noticed in the epithelium of BRAF+ and BRAF− melanoma samples." (PMID 39273022, 2024). "Targeted therapies that specifically inactivate mutated BRAF protein using BRAF inhibitor (BRAFi), such as vemurafenib (PLX4032), have yielded significant positive outcomes in patients with BRAF mutant melanoma." (PMID 38650694, 2024). "Since the BRAF + MEK inhibitor combination is what the National Health Insurance Fund reimburses in Hungary for the first-line treatment of BRAF mutant advanced melanoma, 97.5% of the patients included in the study received targeted therapy in the first line." (PMID 39272837, 2024). "Instead, eIF4F activity is essential for controlling ERK MAPK signaling flux in treatment-naïve human melanoma cells bearing NRAS and BRAF oncogenic mutations." (PMID 39436655, 2024).
melanoma (continued). "Melanoma is well known for its high mutation burden, and mutations leading to increased MAPK signalling (including BRAF, RAS and NF1)." (PMID 39092608, 2024). "Overall, bulk RNA-seq data revealed elevated levels of B cells in samples of metastatic BRAF-mutant melanoma and CD8+ T cells in wild-type metastatic samples." (PMID 39336897, 2024). "Binimetinib is an oral selective MEK 1/2 inhibitor currently FDA approved in the US for use in combination with BRAF inhibitor encorafenib in adult patients with unresectable BRAFV600 altered melanoma and non-small cell lung cancer." (PMID 39759151, 2024). "Given the role of mutations in BRAF and MEK in melanoma progression, BRAF/MEK inhibition has been investigated in combination with T-VEC to augment its activity in tumor cells." (PMID 39602056, 2024). "We also investigated SNAI1 expression among dysplastic nevi and melanoma subgroups and revealed higher SNAI1 expression in BRAF+ and BRAF– melanoma samples than in dysplastic nevi and melanoma in situ." (PMID 39273022, 2024). "Targeted therapy for BRAF-mutant melanoma generally achieves excellent tolerance with low toxicity; however, resistance to therapy typically emerges after 12–18 months of treatment." (PMID 39336897, 2024). "Briefly, WM9 and Hs294T melanoma cells were cultured in increasing concentrations of BRAF and MEK inhibitors (vemurafenib and cobimetinib, respectively) starting at 0.05 μM for both drugs." (PMID 39175042, 2024). "In a study of patients with BRAF-mutant and BRAF-wild-type melanoma, BRAF-mutant tumors exhibited a higher degree of differential gene expression in comparison to BRAF-wild-type tumors of metastatic samples." (PMID 39336897, 2024). "One of the major functions of c‐MYC overexpression in melanoma progression is sustained inhibition of BRAF or RAS‐dependent cellular senescence, and when c‐MYC is lost or inhibited, it induces melanoma cellular senescence." (PMID 39161800, 2024). "This is contrary to the role of purinergic signaling in BRAF-mutant melanoma, which enhances drug tolerance via ppERK reactivation during BRAFi therapy." (PMID 39001489, 2024). "presented real‐world evidence supporting the utilization of anti‐PD‐1 antibodies and BRAF/MEK inhibitors for postoperative adjuvant melanoma across 39 centers in Germany, Austria, and Switzerland." (PMID 38212945, 2024). "successfully created several zebrafish ‘Fin’ melanoma systems that are driven by genes such as CRKL, GAB2 and NF1, analogous to human melanomas that lack BRAF/KIT/NRAS alterations." (PMID 39627834, 2024). "The effects of combined therapy with disulfiram or its metabolite diethyldithiocarbamate and the MEKi trametinib were evaluated in a series of BRAF-WT melanoma cell lines by measuring cell viability and apoptosis induction." (PMID 38263136, 2024). "For BRAF wild-type melanoma, new targeted therapies are being explored, particularly those involving the mitogen-activated protein kinase (MAPK) pathway." (PMID 39329914, 2024). "Immunohistochemical markers and melanoma driver mutations, such as the proteins Melan-A, HMB-45, and S100, as well as the BRAF gene, respectively, provide further diagnostic information for patients with suspected malignant melanoma." (PMID 39228985, 2024). "Studies have shown the glutamine dependency of A375, SKMEL5, and G361 melanoma-resistant cells to BRAF inhibitors." (PMID 38339003, 2024). "Stratification of TOT by 6, 9 and 12 months showed that the probability of TOT differ between gender, age, BRAF status and melanoma stage." (PMID 39517999, 2024). "BRAF is a protooncogene known for its tumorigenic activity in melanoma, hairy cell leukemia, non–Hodgkin lymphoma, thyroid, ovarian, lung, and colorectal cancers." (PMID 38919805, 2024).
melanoma (continued). "MEK inhibitors (MEKi) were shown to be clinically insufficiently effective in patients suffering from BRAF wild-type (BRAF WT) melanoma, even if the MAPK pathway was constitutively activated due to mutations in NRAS or NF-1." (PMID 38263136, 2024). "Following the clinical success from the combined use of BRAF and MEK inhibitors in BRAFV600E-mutant melanoma, the BRAF and MEK inhibitor combination was systematically evaluated in the context of BRAFV600E-mutant NSCLC." (PMID 38731852, 2024). "Due to the high costs associated with drug development, a promising strategy to improve the efficacy of MEKi in BRAF WT melanoma is to repurpose an already approved drug and combine it with a generally effective MEKi like trametinib." (PMID 38263136, 2024). "Regarding melanoma treatment, three combinations of BRAF and MEK inhibitors have received approval from the FDA: vemurafenib plus cobimetinib, dabrafenib plus trametinib, and encorafenib plus binimetinib." (PMID 39582535, 2024). "In a previous study, the nodular histological subtype of primary melanoma was found to be an independent and significant prognostic factor for mortality in metastatic patients treated with BRAF ± MEK inhibitors." (PMID 39272837, 2024). "Abnormal rates of autophagy and its related genes such as Atg5 and Sqstm1/p62 have been found within BRAF-mutant melanoma samples." (PMID 38732242, 2024). "In SKMEL5 cell lines and MM099 short-term melanoma cell culture and 1205Lu xenografts in mice, targeting DDR with imatinib was shown to increase the efficacy of BRAF inhibitors, counteract collagen remodeling, and delay melanoma recurrence." (PMID 39594665, 2024). "BRAF mutation status guides targeted therapy choices, while immunological features of the TME influence the efficacy of immunotherapeutic approaches in melanoma." (PMID 39061208, 2024). "For instance, in melanoma treated with a BRAF inhibitor, cancer cells became hypersensitive to small-molecule inhibitors of OXPHOS." (PMID 39501277, 2024). "Mutation in the BRAF and NRAS accounts for 50 and 30 % of the total cause of melanoma, respectively." (PMID 38560710, 2024). "In melanomas treated with BRAF and MEK inhibitors, PAX3 and MITF expression increases and appears to contribute to the early drug tolerance state." (PMID 38473380, 2024). "To verify this, we used the active metabolite of DSF in its copper-bound form CuET in our preclinical in vitro studies and combined it with the MEKi trametinib to treat BRAF-WT melanoma cells." (PMID 38263136, 2024). "For example, melanomas in young patients with lowcumulative exposure to solar ultraviolet radiation are 2.7 times more likely to showmutations in the BRAF gene (proto-oncogene B-Raf)." (PMID 39116405, 2024). "In this context, the detection of the BRAF V600E mutation opens the door to an agnostic approach based on targeted therapies, such as BRAF inhibitors, which are effective in other malignancies like melanoma, colorectal cancer, and certain thyroid tumors." (PMID 39392364, 2024). "Our study highlights the value of NGS in detecting BRAF, NRAS mutations and RAF fusions, expanding possibilities for targeted therapies in malignant melanoma." (PMID 38470950, 2024). "Patients with both BRAF and NRAS mutations have a poorer prognosis compared to those bearing either NRAS wild-type or BRAF-mutant melanoma." (PMID 38396984, 2024). "These drugs have shown significant efficacy in patients with BRAF-mutant melanomas by blocking the excessive signaling and suppressing tumor growth." (PMID 38247727, 2024). "Durability of responses are also limited with approximately 30% and 50% of melanoma patients progressing after one year of treatment with immune checkpoint or BRAF/MEK inhibitors." (PMID 38241976, 2024). "Semi-quantitative analysis demonstrated the moderate immunoreactivity in the epithelium of BRAF+ and BRAF− melanoma samples, compared to other observed sample groups." (PMID 39273022, 2024).
melanoma (continued). "Our previous study found that MAPKi treatment can activate JAK2/STAT3 signal in BRAF mutant melanoma." (PMID 38822350, 2024). "Quantitative cell evaluation of LOXL3, NES, and SNAI1 immunoreactivity in dysplastic nevi, melanoma in situ, and BRAF− and BRAF+ melanoma was performed by determining the section percentage area of the epidermal region." (PMID 39273022, 2024). "We wanted to gain mechanistic insight into how BRAF depletion exerts this effect on melanoma TEM and actin reorganization." (PMID 39457016, 2024). "In summary, the combined inhibition of ERK and Mcl-1 shows promising efficacy in both BRAF-mutant and wild-type melanoma cells, offering a potential new strategy to overcome drug resistance." (PMID 39329914, 2024). "Targeted therapies against mutant BRAF are effectively used in combination with MEK inhibitors (MEKi) to treat advanced melanoma." (PMID 38839106, 2024). "The expression of the MCL splice variant is related to the BRAF mutational status in melanoma cell lines; MCL1L and MCL1S mRNA expression is increased in BRAF V600E mutant melanoma cells." (PMID 38462618, 2024). "In this retrospective analysis, patients with advanced BRAF-mutated melanoma treated with first-line immunotherapy had a significantly longer PFS and OS than those treated with first-line BRAF/MEKi." (PMID 38450188, 2024). "Targeted therapy, utilizing a BRAF inhibitor such as dabrafenib in combination with a MEK inhibitor like trametinib, is approved for melanoma and NSCLCs with the BRAF V600E mutation." (PMID 39040442, 2024). "Normal baseline serum LDH and <3 metastatic sites were associated with significant PFS and OS benefit in patients with unresectable advanced melanoma treated with BRAF + MEK inhibitors." (PMID 39272837, 2024). "Firstly, we evaluated the impact of healthy donor neutrophils on the viability of melanoma cells after BRAF/MEK inhibition using in vitro cocultures." (PMID 38730718, 2024). "Frequently denoted as p16 or INK4a/ARF, mutations in the CDKN2A gene are a less commonly explored aspect within the context of melanoma when compared to BRAF alterations." (PMID 38792946, 2024). "BRAF and MEK inhibitors: These inhibitors target the BRAF and MEK proteins in the MAPK/ERK signaling pathway, which is often mutated in cancers such as melanoma." (PMID 39001539, 2024). "This provided substantial quality-adjusted survival gains to patients with BRAF wild-type advanced melanoma." (PMID 38473355, 2024). "Identification of the essential role of the oncogenic BRAF and NRAS mutations activating ERK signaling for melanoma development and survival has led to the development of pharmacological BRAF and MEK inhibitors." (PMID 39436655, 2024). "For example, melanoma cells that acquired resistance to anti-BRAF treatments largely rely on complex-I-dependent OXPHOS." (PMID 38790264, 2024). "In conclusion, these are the first data for encorafenib in combination with binimetinib evaluating a high-dose regimen in patients with BRAF V600-mutant melanoma with brain metastasis." (PMID 38725995, 2024). "Although BRAF and MEK inhibitors are effective in treating melanoma, the oral side effects associated with their use, such as gingival hyperplasia, are often overlooked when assessing their suitability for individual patients." (PMID 39797148, 2024). "Our results reveal a significant increase in LOXL3 expression and the highest NES expression in BRAF+ melanoma compared to BRAF−, dysplastic nevi, and melanoma in situ." (PMID 39273022, 2024).
melanoma (continued). "The overall survival of patients with BRAF-positive mutant melanoma has improved significantly since the discovery of targeted therapy, although the prognosis of NRAS-mutated patients tends to be far poorer." (PMID 38127894, 2024). "Class I alterations are the dominant form of BRAF alteration in melanomas, thyroid, colorectal, and ovarian cancers." (PMID 39018217, 2024). "TIL therapy has emerged as a personalized immunotherapeutic approach for patients with BRAF-mutant melanoma." (PMID 39336897, 2024). "Among them, BRAF V600E/K stands out as the most effective target and has become the only target in melanoma targeted therapies approved by the food and drug administration." (PMID 39025927, 2024). "BRAF (v-raf murine sarcoma viral oncogene homolog B1)/MEK (mitogen-activated protein kinase kinase) inhibitors are used for melanoma treatment." (PMID 39175042, 2024). "Previous studies have shown the clinical benefit of rechallenging the RAF pathway in melanoma patients previously treated with BRAF inhibitors." (PMID 38532456, 2024). "In contrast to targeted therapy for BRAF V600E/K mutant melanomas, immune checkpoint inhibitors (ICI) have shown enhanced clinical outcomes in melanoma patients irrespective of the presence of a particular oncogenic mutational signature or biomarker." (PMID 39025927, 2024). "We performed RNA-sequencing after culturing the A375 melanoma cell line for 24h in the absence or presence of a combination of BRAF- and MEK-inhibitors (hereinafter termed MAPK inhibitors [MAPKi])." (PMID 38690580, 2024). "Several lines of evidence indicate that the capacity of melanoma persister cells to tolerate BRAF/MEK inhibition relies in large part on the reprogramming of the cell biosynthetic processes, including mRNA translation and/or mitochondrial energy production." (PMID 38755661, 2024). "RFS, OS, and melanoma‐specific survival (MSS), and response to subsequent treatment in 589 stage III patients (232 BRAF‐mutated) receiving adjuvant PD‐1 antibodies (n = 479) or targeted therapy (n = 110) have been reported." (PMID 38212945, 2024). "Although these targeted therapies have greatly improved the prognosis of patients with advanced BRAF-mutant melanoma, they also have two major limitations: on the one hand, acquired resistance to BRAF inhibition typically develops after a median of 9–12 mo." (PMID 38839106, 2024). "It has been demonstrated that patients with NRAS mutant melanoma were older than 55 years and had a previous history of UV exposure, and thus, higher pro-inflammatory conditions than those with BRAF mutant tumors." (PMID 38396984, 2024). "Despite the association of NRAS-mutant tumors with chronic sun damaged skin, it is reported that UV signature lesions (C>T and CC>TT) are present in a similar proportion of NRAS- and BRAF-mutant melanomas." (PMID 38927967, 2024). "The promising results in BRAF mutant melanomas have led to trials of dual dabrafenib plus trametinib therapy in non-small cell lung cancer." (PMID 39234402, 2024). "With the advancement of systemic therapy, including immune checkpoint blockade and BRAF inhibitors, the abscopal effect in melanoma is being increasingly reported." (PMID 39618779, 2024). "Medical records of 140 patients diagnosed with advanced melanoma between 2011 and 2021 were retrospectively reviewed to extract demographic, BRAF status, treatment, performance status, and survival data." (PMID 38450188, 2024). "A recent phase III trial demonstrated substantial improvements in overall survival among BRAF mutant, advanced melanoma patients who received vemurafenib treatment compared with those treated with dacarbazine." (PMID 38534309, 2024). "We therefore propose that TMEM16A has the potential to be a therapeutic target for the treatment of BRAF-mutant malignant melanomas." (PMID 39070550, 2024).